HK1 (hexokinase 1)
Diseases named in the same sentence as HK1 in open-access papers (continued):
Sharing a sentence is not in itself a finding about the gene and the disease.
cancer (continued). "The four isoforms of HK (HK1, HK2, HK3, and HK4) are highly expressed on the surface of cancer cells and cover the outermost layer of mitochondria via transmembrane voltage-dependent anion channels." (PMID 41341097, 2026). "There are four subtypes of HK, namely HK1, HK2, HK3 and HK4, among which HK1 and HK2 play a role as drivers of cancer cell glycolysis." (PMID 39895802, 2025). "Pharmacological inhibition of NPPS-HK1 axis using NPPS inhibitor Enpp-1-IN-1 or HK1 inhibitor 2-deoxyglucose (2-DG), or genetic interfere with NPPS suppressed RAS-mutant cancers in vitro and in vivo." (PMID 39506063, 2025). "TGF-β activates the AKT signaling pathway to enhance HK1 and HK2 expression in cancer cells, leading to increased glucose consumption, ATP production, and precise modulation of cell cycle distribution." (PMID 39895802, 2025). "In vitro and in vivo studies have shown that, compared to HK1, HK2 is highly expressed in cancers, particularly in highly glycolytic cancers, as HK2 can partially enhance glucose flux." (PMID 38538285, 2024). "Several studies have confirmed that GLUT1, HK1 and HK2 expression is closely related to the progression of malignant tumors." (PMID 38514913, 2024). "In cancer cells, the expression of hexokinase 2 (HK2) is induced alongside the hexokinase 1 (HK1) that is also present in normal cells, thereby doubling the capacity for this critical step." (PMID 39479443, 2024). "Cancer cells increase their own HK1 level by hijacking the IEV HK1 secreted by HSCs, and then increase the level of glycolysis in cancer cells to promote cancer cell proliferation." (PMID 39765609, 2024). "The observation that most normal cells express HK1 while cancer cells express HK1 and HK2 stimulated interest in reducing HK2 activity in cancers." (PMID 37109475, 2023). "HK1 is generally expressed in most adult tissues, whereas HK2 is highly expressed in many fetal tissues and cancer cells." (PMID 36192599, 2022). "While HK1 is widely and constitutively expressed, HK2 is selectively expressed during embryogenesis and in cancer where it has been shown to induce proliferation and inhibit cell death." (PMID 35902556, 2022). "HK1 is widely expressed in numerous organs, and HK2 expression is significantly upregulated in cancer cells, promoting glucose uptake and participation in multiple metabolic pathways." (PMID 36230492, 2022). "The two most abundantly expressed isoenzymes HK1 and HK2 are critical for maintaining an elevated rate of glycolysis in cancer cells." (PMID 36304460, 2022). "Decreased expression of HK1 accelerates tumor malignancy through regulating energy metabolism, and there is an inverse relationship in the expression of HK1 and HK2 in cancer." (PMID 35626002, 2022). "Compared with the three hexokinase isozymes, HK1, HK2, and HK4, the role and mechanism of action of HK3 in cancer is less reported." (PMID 33980323, 2021). "HK1 is ubiquitously expressed and is the main hexokinase expressed in most normal adult tissues, while HK2 is highly expressed in many cancers and constitutes the predominant hexokinase in only a limited number of adult tissues." (PMID 34378321, 2021). "Among all four isoforms of HK (HK1, HK2, HK3, and HK4), HK2 was found to be highly expressed in patients with carcinomas and considered the most efficient isoform in aerobic glycolysis." (PMID 34368116, 2021). "HK1 is widely expressed in adult tissues and is considered the housekeeping isoform of hexokinase, and HK2 is highly expressed in many cancer cells." (PMID 33275593, 2020). "There are four important isoforms of mammalian hexokinase, designated HK1–4; in particular, isoform 2 (HK2) is dysregulated in multiple cancers, including CRC." (PMID 32878019, 2020). "Currently, KRAS4A, the unique palmitoylation-depalmitoylation cycle of the RAS isoform, is known to colocalize with HK1 on the outer mitochondrial membrane, and HK1, as a downstream effector of KRAS4A, can enhance glycolytic flux and cancer progression." (PMID 33256814, 2020).
cancer (continued). "Cancer cells predominantly express SLC2A1 (GLUT1) and SLC2A3 (GLUT3) to transport glucose across the cell membrane and Hexokinase 1 and Hexokinase 2 to phosphorylate glucose." (PMID 31784510, 2019). "Although there are four HK isoforms, the isoforms HK1 and HK2 seem to be overexpressed in cancer cells." (PMID 29629339, 2018). "HIF-1α induces the over-expression of several glycolytic proteins including glucose transporters (i.e., GLUT1 and GLUT3), and enzymes such as hexokinase-1 (HK1), HK2 and LDHA in cancer cells." (PMID 30619850, 2018). "Most tumors express both HK1 and HK2, and subsets of cancers from a wide variety of tissues of origin express only HK2." (PMID 29988332, 2018). "In addition, how the HK1 gene is silenced in the HK1−HK2+ subsets of cancers is unknown." (PMID 29988332, 2018). "The CRISPR Cas9 method was used to establish isogenic HK1+HK2+ and HK1−HK2+ cell lines to evaluate HK1−HK2+ cancer cell sensitivity to the combination therapy." (PMID 29988332, 2018). "Among these isozymes, both HK1 and HK2 play critical roles in promoting cell proliferation and survival in malignant cancers." (PMID 29721175, 2018). "HK1 is highly expressed in normal tissues of the human body, and its distribution is wider than that of HK2 (only expressed in cancer cells)." (PMID 28427443, 2017). "It has been suggested that while HK1 is ubiquitously expressed in the majority of adult tissues, HK2 is expressed at high levels in many cancer cells." (PMID 25426557, 2015). "Additional strategies to target Hexokinase 1 will have to follow the approach outlined here of targeting a cancer-specific pathway that drives Hexokinase 1 protein levels or activity rather than targeting Hexokinase 1 directly." (PMID 36697489, 2023). "In conclusion, we demonstrate RB1 or HK1 as critical regulators of the cellular bioenergetic profile and identify the altered tumor metabolism as a potential therapeutic target for cancers lacking functional Rb protein." (PMID 36291051, 2022). "We show that the lack of HK1 allows the Rb-null cancer cells to expand their flexibility of fuel choices, using glutamine and fatty acids for TCA anaplerosis." (PMID 36291051, 2022). "Besides GLUT1, other key metabolic enzymes (e.g., HK1/2, PFKL, and LDHA) required for the glycolysis pathway of cancer cells were also investigated herein." (PMID 32774674, 2020). "The variable result of HK-1 expression analysis in cancer tissues and the lack of global up-regulation in this study is not surprising." (PMID 32372141, 2020). "As HK1 has been shown to be the most important glycolytic enzyme that controls the glycolytic pathway, this suggests that the regulation of HK1 by KRAS4A will have a substantial effect in cancer initiation and progression." (PMID 32879916, 2020). "While HK2 is highly expressed in the majority of cancers, cancer subtypes with differential HK1 and HK2 expression have not been characterized for their sensitivities to HK2 silencing." (PMID 29988332, 2018). "However, the functional roles or effects of both HK1 and HK2 in glucose metabolism and the malignant progression of cancers are not fully understood, especially when their expression levels are decreased or low." (PMID 29721175, 2018). "Both HK1 and HK2 drive cancer aerobic glycolysis—glucose consumption and lactic acid production." (PMID 29988332, 2018). "There was an inverse correlation between the expression of HK1 and HK2 in human cancer cells." (PMID 29721175, 2018). "HK1 and HK2 expression in the Cancer Cell Line Encyclopedia dataset was analyzed." (PMID 29988332, 2018). "Thus, either HK1 or HK2 overexpression in tumors is thought to provide both a metabolic benefit and an anti-apoptotic capacity that give the cancer cells a growth advantage and increase their resistance to anticancer therapy." (PMID 29721175, 2018). "Our results suggest that HK1 and HK2 could be the key therapeutic targets for reducing aerobic glycolysis in examined cancers." (PMID 28105937, 2016).
cancer (continued). "In the present study, we found that the over-expression of the three glycolysis associated genes, GLUT1, HK1, and HK2, was not consistently seen in the NETs, which confirms the lower glucose utilization of NETs compared to several other cancer entities." (PMID 26824929, 2013). "The fact that kallistatin, which rapidly binds hK1 and inhibits its activity in vitro, blocks the strengthening action of GIST882 cells on HUVEC networks argues in favour of hK1 as a promoter of cancer angiogenesis." (PMID 20859288, 2010). "HKs (HK1 and HK2), PFK1 and PFK2, G6PD, pyruvate kinase, phosphoglycerate dehydrogenase (PHGDH), lactate dehydrogenase, phosphoglycerate kinase 1 (PGK1), enolase (ENO), isocitrate dehydrogenase (IDH), and glucose transferase (GLUT) serve as ideal pharmacological targets to treat cancer." (PMID 36984785, 2023). "In addition, knockdown of HK2 was found to inhibit cancer development in mouse models and, more importantly, did not activate HK1 expression." (PMID 36230492, 2022). "We first found that YTHDC1 mRNA expression was downregulated in cancer tissues compared with nontumor tissues, and there was a positive association between YTHDC1 and miR-30d and a negative association between YTHDC1 and RUNX1, SLC2A1, HK1." (PMID 34021267, 2021). "We conclude (i) that inhibition of HK2-driven glycolysis, OXPHOS, and FAO is likely to be a pan-tumor precision therapy approach to HK1−HK2+ tumors, regardless of their tissue of origin, and (ii) that cancer therapies that involve HK2 inhibition will be restricted to tumors that do not express HK1." (PMID 29988332, 2018). "Cancer subtypes with differential HK1/HK2 expression have not been characterized." (PMID 29988332, 2018). "Unlike HK1+HK2+ cancers, HK1−HK2+ cancers are sensitive to HK2 silencing-induced cytostasis." (PMID 29988332, 2018). "However, most previous studies on HK2 in cancer did not examine the contribution of HK1 to cancer glycolysis." (PMID 29988332, 2018). "Furthermore, HIF-1α has been demonstrated to act as a key regulator in glycolysis, HIF-1α is the best-known transcriptional regulators controlling expression of glycolysis genes, such as HK1, HK2, and LDHA, whose expression levels are highly elevated in cancer cells." (PMID 29137372, 2017). "However, these cancer cells also express HK1, whereas human HCC cells generally do not express HK1." (PMID 29386513, 2018). "In addition, HK1 knockdown induced the EMT phenotype and accelerated tumor malignancy; in contrast, HK2 silencing did not cause any morphological change and did not affect cancer cell growth and migration." (PMID 29721175, 2018). "Mechanistically, in RAS-mutant cells, NPPS interacted with the N-terminal region (aa 22–474) of hexokinase 1 (HK1) and promoted glycolysis and cancer growth and survival, independent of its canonical nucleotide-metabolizing activity." (PMID 39506063, 2025). "By using various cancer databases, HK2, but not HK1, positively correlates with HNSCC progression in a stage-dependent manner." (PMID 32195170, 2020). "We have studied HK2 knockdown in a large panel of naturally existing HK1+HK2+ and HK1−HK2+ cancer cells and found that only HK1−HK2+ cancer cells but not HK1+HK2+ cells as defined by mRNA and Western blot analyses are sensitive to HK2 knockdown." (PMID 29988332, 2018). "In vitro studies demonstrated that VDA-1102 selectively detaches HK2, but not HK1, from VDAC1 leading to cancer cell apoptosis as well as glycolysis inhibition and reduction in lactate secretion, culminating in proliferation inhibition." (PMID 30400835, 2018). "HK1 and HK2 are more tightly bound to VDAC in cancer cells than in nonmalignant cells." (PMID 24648844, 2014).
tumor (251 papers, 1996 to 2026). "This would then cause the loss of HK1 and then lead to tumor death, corroborating the treatment and prognosis of BC." (PMID 39684297, 2024). "In our study, HK1 had a high conservation ratio and pathogenic variant, and its loss leads to tumor cells by deregulation and activation of apoptosis, corroborating our study since the mutations found here are pathogenic." (PMID 39684297, 2024). "The elevated level of hexokinase 1 (PITRM1-HK1 fusion event) causes tumor cells to avoid apoptosis; the fusion of BCR-NDUFAF6 (ABL) is amenable to targeting in patients with SS as well as that of CTLA4 and CD28 fusion." (PMID 36291756, 2022). "Taken together, miR-30d plays a tumor-suppressive role in resisting pancreatic tumorigenesis via a selective target loss of HK1 and SLC2A1-regulator RUNX1, subsequently resulting in inhibition of the Warburg effect." (PMID 34021267, 2021). "In has been shown that in tumor cells cytosolic HK1 and HK2 were tightly associated to the voltage-dependent anion channel (VDAC) in the mitochondrial membrane." (PMID 28105937, 2016). "Results of qRT-PCR analysis showed gradual increases in GLUT1 and HK1 expression with higher tumor risk grade." (PMID 26509967, 2015). "Intravenous injection of lEVs derived from control moHSCs but not those derived from HK1 knockdown moHSCs notably promoted the growth of Hepa1-6 cell–derived orthotopic xenograft tumors, associated with elevated protein levels of HK1 and Ki67, a marker of cell proliferation, in tumor tissues." (PMID 36192599, 2022). "Among the isoforms of GLUT and HK, GLUT1 and HK1 expression increased with higher tumor risk grade." (PMID 26509967, 2015). "Enzyme-linked immunosorbent assay revealed high levels of hK1 in the examined tumours." (PMID 20859288, 2010). "NR6A1 activated glycolysis through p-mTOR signaling and the miR-302a/HK1 axis and ultimately promoted tumor cell proliferation." (PMID 41219936, 2025). "HK1 levels were low in HCLs, whereas HK2, often associated with tumor metabolism, was significantly upregulated in HCLs compared to all primary cells but remained low in HepaFH3." (PMID 40862732, 2025). "It was shown that HK1 also mediates sorafenib resistance, and sorafenib treatment of human HCC patient-derived xenografts (PDXs) induced HK1 and HK1 levels correlated with tumor growth." (PMID 39682130, 2024). "KRAS mutation has been reported to directly regulate the enzymatic activity of hexokinase 1, thereby increasing glucose utilization by tumor cells." (PMID 38384814, 2024). "Comparative analysis showed that genes such as BTG3, PCMT1 and HK1 are gradually increasing in epithelial/malignant cells from tumor tissues compared to these cells from normal tissues." (PMID 39575251, 2024). "KRAS4A enhances the rate of glucose uptake and regulates glucose metabolism in tumor cells by inhibiting the allosteric regulatory effect of HK1." (PMID 37834257, 2023). "Studies have found that c‐Src phosphorylates HK1 at Tyr732, which promotes the glycolysis rate of tumor cells and their proliferation, invasion, and metastasis abilities." (PMID 37143582, 2023). "It is worth noting that all Khib of HK1 are upregulation trends in OACC-tumor tissues, especially at K488 (fold change:5.39) and K187 (fold change: 2.43)." (PMID 37741973, 2023). "The mRNA expression of these genes in TCGA-PRAD samples was determined, and in both non-paired and paired samples, HK2, HK3 and ADPGK were overexpressed, while GCK and HK1 were downregulated in tumor samples compared with normal tissues." (PMID 38082365, 2023). "Tumors derived from the siTFRC#2-HK1-EBV group were smaller, and the mean tumor weight was also lighter in siTFRC#2-HK1-EBV group (61.3 mg) compared with those in the siCtrl-HK1-EBV group (178.4 mg)." (PMID 37644594, 2023).
tumor (continued). "In our snATAC-seq data, we also observed motifs of HIF1A in the PFKP, ENO2, and HK1 open promoter regions that are more accessible in tumor cells, consistent with the previous reports of HIF1A regulating these genes." (PMID 36973268, 2023). "In various cancers, including CRC, HK-1 and HK-2 are upregulated to meet the high metabolic state of tumor cells and accelerate tumor cell proliferation, migration, and invasion." (PMID 37576895, 2023). "Recent studies have indicated that KRAS plays a key role in coordinating tumor metabolic reprogramming by upregulating the transcription of multiple key glycolysis enzymes, such as HK1/2, PFK1, LDHA, and GLUT1." (PMID 36994237, 2023). "In instances where tumor cells experience a severe glucose deficit, HK1 assumes a more prominent role in facilitating glycolytic reactions compared to HK2, owing to its lower Km." (PMID 37741973, 2023). "tRF-19-Q1Q89PJZ upregulation inhibited PC cell proliferation and metastasis in vivo and suppressed HK1 expression in tumor tissues." (PMID 37892195, 2023). "c‐Src phosphorylates HK1 at Tyr732 to promote the glycolysis rate of tumor cells and their proliferation, invasion, and metastasis abilities." (PMID 37143582, 2023). "HK1 expression was clearly detected in orthotopic xenografts derived from HK1 knockdown Hepa1-6 cells in Hk1f/f mice but not in Hki1f/f;Gfap-Cre mice, suggesting that the HK1 protein in tumor cells is likely transferred from HSCs in mice." (PMID 36192599, 2022). "Through an integrated omics analysis of the transcriptomics and metabolomics of Rb, we uncovered a significantly altered tumor-specific metabolic circuit that reduces its dependence on glycolytic pathways and is governed by Rb1 and HK1." (PMID 35626705, 2022). "Recently, HK1 was suggested to act as an effector regulated by K-Ras4A to promote tumor metabolic reprogramming, and overexpression of HK1 was found to predict poor prognosis in colorectal cancer." (PMID 36192599, 2022). "When lEV HK1 secretion in HSCs was abolished by mutation of HK1 6CS, HSC-derived lEVs lost their ability to promote xenograft tumor growth, and HK1 and Ki67 expression was reduced in tumor tissues." (PMID 36192599, 2022). "In an additional set of Rb tumor samples and pediatric healthy controls, we further validated differences in the expression of HK1 and E2F2." (PMID 35626705, 2022). "PDNPA administration significantly reduced the tumor number, accompanied by decreased HK1 and Ki67 expression in tumor tissues." (PMID 36192599, 2022). "High expression of HK1 is observed in various tumors, possibly driving higher glycolysis in those cases to fulfill the tumor cell’s energy demands." (PMID 36291051, 2022). "HSC-specific knockout of HK1 was clearly observed in these mice (Hk1f/f;Lrat-Cre mice), which was accompanied with the retarded tumor growth and suppressed expressions of HK1 and Ki67 in tumor tissues." (PMID 36192599, 2022). "When these mice were crossed with Gfap-Cre mice, Nur77 was specifically deleted in the HSCs, which clearly promoted the growth of orthotopic xenograft tumors, leading to enhanced expression of HK1 and Ki67 in tumor tissues." (PMID 36192599, 2022). "This transfer of HK1 was accompanied by the growth of xenografts and the proliferation of tumor cells (Ki67)." (PMID 36192599, 2022). "The present study identified and quantified HK-1 enzyme expression in the tumor tissue after treatment." (PMID 35936786, 2022). "Together, these in vivo results consistently confirm that lEV HK1 from the fibrotic microenvironment is hijacked by HCC cells to promote tumor progression." (PMID 36192599, 2022). "As well documented, the high glycolytic flux in tumor cells relys on glycolysis-associated signature, including GLUT3, SRC-3, hexokinase 1 (HK1), as well as lactic dehydrogenase A (LDHA), leading to production of pyruvate, alanine, and lactate." (PMID 34906161, 2021).